PPARG (peroxisome proliferator activated receptor gamma)
Diseases named in the same sentence as PPARG in open-access papers (continued):
Sharing a sentence is not in itself a finding about the gene and the disease.
osteoarthritis (continued). "Besides its well-known regulatory role in lipid and glucose metabolism, PPARγ can repress the inflammatory process, and previous studies have shown its activation suppressed IL-1β-induced inflammation in human osteoarthritis chondrocytes." (PMID 38041147, 2023). "PPARG has been proposed as a therapeutic target for osteoarthritis, therefore its regulation axis could provide possible intervention points." (PMID 35088088, 2022). "PPARγ suppression by diacerein can alleviate oxidative stress and osteoarthritis in mice." (PMID 35842709, 2022). "Consequently, PPARγ activation reduced experimental arthritis and cartilage-specific knockout of PPARγ resulted in development of osteoarthritis in mice." (PMID 32785018, 2020). "In view of evidence that chondrocyte‐specific deletion of PPARγ exacerbates osteoarthritis, we examined whether the increased porosity seen in aged PPARγΔPrx1 mice was due to osteoarthritic changes in the knee." (PMID 33048436, 2020). "We and others have previously shown that PPARγ activators display anti-inflammatory and chondroprotective properties in vitro and improve the clinical course and histopathological features in an experimental animal model of osteoarthritis (OA)." (PMID 17386086, 2007). "Therefore, inhibition of chondrocyte ferroptosis by PPARγ may be a therapeutic approach for osteoarthritis." (PMID 37620972, 2023). "This suggests PPARγ may be an attractive therapeutic target for osteoarthritis." (PMID 38041147, 2023). "Thus, lack of adipocyte‐derived catabolic factors might explain why osteoarthritis is attenuated by deletion of PPARγ in Prx1‐Cre targeted cells." (PMID 33048436, 2020). "In an osteoporotic osteoarthritis animal model, PEMF therapy effectively prevented cartilage and subchondral bone destruction by upregulating PPARγ and inhibiting chondrocyte apoptosis, inflammation and autophagy." (PMID 41588476, 2026). "PPARγ controls ESCRT-dependent FLSs exosome biogenesis and alleviates chondrocyte osteoarthritis mediated by exosomal cargo ANXA1 protein." (PMID 40678612, 2025). "Moreover, as an anti-inflammatory agent, betulinic acid has been shown to inhibit IL-1β-induced inflammation in human osteoarthritis chondrocytes, an effect that can be reversed by GW9662, a potent synthetic PPARG antagonist." (PMID 40564064, 2025). "Studies have found that mice lacking PPARγ show accelerated development of osteoarthritis compared with wild‐type mice, indicating that PPARγ is essential for maintaining chondrocyte homeostasis." (PMID 37986543, 2024). "PPARγ can regulate the activity of the NF‐κB pathway and participate in the ECM degradation of chondrocytes, anabolism, apoptosis and inflammation, and other pathological processes in osteoarthritis." (PMID 37986543, 2024). "In animal models of adjuvant-induced arthritis, osteoarthritis and neuroinflammation, it has been observed that independent activation of CB2 receptor and PPARγ can inhibit the activation of the canonical transcription factor NF-κB and the mitogen-activated protein kinases (MAPKs)." (PMID 29910713, 2018).
lung adenocarcinoma (34 papers, 2005 to 2025). A carcinoma that arises from the lung and is characterized by the presence of malignant glandular epithelial cells. "Previous studies showed that low PPARG expression was associated with poor prognosis of lung adenocarcinoma (LA) with limited mechanisms identified." (PMID 32395124, 2020). "The results showed that PPARG was positively associated with survival time in lung adenocarcinoma (HR = 0.59, P = 0.00078)." (PMID 29573196, 2018). "It has recently been demonstrated that CAV1 as well as PPARG are associated with a favorable outcome in lung adenocarcinoma, while the cytokine CXCL2 might be a predictor for immunotherapy response." (PMID 34831349, 2021). "In EGFR-TKI-resistant lung adenocarcinoma cells, the PPARγ agonist, efatutazone, has been shown to trigger both apoptosis and cell cycle arrest via modulating the PPARγ/phosphatase and tensin homolog (PTEN)/AKT axis." (PMID 41304753, 2025). "Bioinformatics confirmed that the expression of the PPARG gene can predict outcomes in lung adenocarcinoma and is related to immune cells present in the tumor." (PMID 40646269, 2025). "It has been reported that the activation of PPARγ inhibited the induction of EMT markers in lung adenocarcinoma." (PMID 37048080, 2023). "In lung adenocarcinoma cells treated with transforming growth factor β (TGF-β), a potent EMT inducer, PPARγ activation counteracts the loss of E-cadherin expression and inhibits the induction of mesenchymal markers, thus preventing migration and invasion." (PMID 37048080, 2023). "By detecting the expression of cyclin and PPARγ, we further explored the molecular mechanisms of stigmasterol against lung adenocarcinoma." (PMID 35911149, 2022). "The current study demonstrated that stigmasterol targeted PPARγ and inhibited the viability and tumorigenicity of lung adenocarcinoma cells NCI-H1975." (PMID 35911149, 2022). "It has been clarified that monomer stigmasterol targeted PPARγ and inhibited the viability and tumorigenicity of lung adenocarcinoma cells NCI-H1975." (PMID 35911149, 2022). "In the present study, A-549 lung adenocarcinoma cells were induced with PPARγ agonist, PGZ, and were further evaluated for morphological alterations and Oil Red O staining with expression of metabolism-related transcripts." (PMID 33456717, 2020). "Upon searching published papers and the LncMap database, we identified that five TFs—DDX17, STAT1, PPARG, ETS1, and E2F6—were closely associated with adenocarcinoma of the lung and HCG23." (PMID 32322582, 2020). "C/EBP beta induces elevated IL-6 expression levels frequently observed in human lung adenocarcinomas and interacts with peroxisome proliferator-activated receptor-gamma (PPARG) involved in pathways of transcriptional misregulation in cancer." (PMID 32983988, 2020). "These eight representative datasets revealed that PPARG gene expression levels were decreased in lung adenocarcinoma." (PMID 29573196, 2018). "A previous study reported that PPARγ activation induces mitochondrial β-oxidation subsequently generating mitochondrial ROS, which results in growth inhibition of lung adenocarcinoma H2347 cells." (PMID 29137280, 2017). "“In vitro” PPARγ, β and α protein contents were evaluated in tumor (lung adenocarcinoma A549) and normal(keratinocytes NCTC 2544) human cell lines, treated with naturalor synthetic ligands (DHA or clofibrate)." (PMID 17389773, 2007). "Well-differentiated lung adenocarcinomas present increased frequency for PPARγ expression compared with moderately and poorly differentiated ones." (PMID 15583697, 2005). "Additionally, PPARγ activation enhances tumor-necrosis-factor-related apoptosis-inducing ligand (TRAIL)-mediated apoptosis in lung adenocarcinoma cells by promoting autophagy flux." (PMID 41304753, 2025).
lung adenocarcinoma (continued). "In EGFR-driven lung adenocarcinoma (LUAD), tumor-associated alveolar macrophages (TA-AMs) can reduce EGFR phosphorylation and inhibit LUAD progression by enhancing GM-CSF-PPARγ signaling and suppressing PPARγ-driven signaling to inhibit cholesterol flux toward tumor cells." (PMID 38954021, 2024). "Furthermore, PPARγ activation enhanced TRAIL-induced apoptosis in human lung adenocarcinoma cells via autophagy flux." (PMID 38397426, 2024). "PPARγ agonist efatutazone could induce the cell cycle arrest and apoptosis of EGFR-TKI-resistant lung adenocarcinoma cells via PPARγ/phosphatase and tensin homolog (PTEN)/Akt pathway." (PMID 38397426, 2024). "Based on previous studies, this study put forward the hypothesis that stigmasterol, the main drug monomer of AhBl, targeted PPARγ and inhibited the viability and tumorigenicity of lung adenocarcinoma cells NCI-H1975." (PMID 35911149, 2022). "Since M. tb infection induces COX-2 production and COX-2 has been linked to regulation of Mcl-1 production in human lung adenocarcinoma cells, we first determined if COX-2 is important for PPARγ activity and the production of Mcl-1 during M. tb infection of human macrophages." (PMID 29928066, 2018). "We therefore hypothesized that PPARG, LXRα, and ABCA1 were related to tumor‐suppressive effects against acquired gefitinib‐resistant lung adenocarcinoma cells, and efatutazone, the novel third‐generation PPARG agonist, could be a potentially useful choice for patients with lung adenocarcinoma." (PMID 29573196, 2018). "PPARγ agonist efatutazone and gefitinib have been indicated to synergistically inhibit the proliferation of EGFR-TKI-resistant lung adenocarcinoma cells via the PPARγ/PTEN/Akt pathway." (PMID 34889713, 2021).
non-small cell lung carcinoma (34 papers, 2005 to 2026). A group of at least three distinct histological types of lung cancer, including non-small cell squamous cell carcinoma, adenocarcinoma, and large cell carcinoma. "The activation of the PPARG transcription factor is linked to reduced non-small cell lung cancer (NSCLC) growth." (PMID 40646269, 2025). "We investigated PPARγ-related molecules affected by sodium arsenite (NaAR) in non-small cell lung cancer (NSCLC) cells using immunochemical, gene knockdown, and immunoprecipitation approaches." (PMID 42041527, 2026). "CB11, a novel PPARγ agonist, has emerged as a potential anti-cancer drug in targeting therapy for non-small cell lung cancer (NSCLC), demonstrating efficacy in overcoming radioresistance in NSCLC." (PMID 38383403, 2024). "The current study focuses on the effect of DHA with different molecular forms on the PPARγ-mediated NF-κB signal in 95D non-small-cell lung cancer cells apoptosis." (PMID 36286423, 2022). "Hypoxia induces the stabilization of Hif-1α, which suppresses PPARγ in non-small-cell lung cancer (NSCLC)." (PMID 35954274, 2022). "Peroxisome proliferator-activated receptor γ (PPARγ) agonists frequently induce cell death in human non-small-cell lung cancer (NSCLC) cells." (PMID 32958825, 2020). "The combination of PPARg agonists with COX-2 inhibitors has demonstrated a synergistic tumor-suppressing effect in studies on non-small-cell lung cancer." (PMID 32850012, 2020). "In non-small-cell lung cancer, PPARg stimulation inhibits the neoplastic process by regulating PTEN protein expression." (PMID 32850012, 2020). "Prostacyclin analogs, in addition to their anti-inflammatory effects, selectively increase peroxisome proliferator-activated receptor gamma (PPARγ) activity in non-small cell lung cancer." (PMID 24840047, 2014). "The anti-proliferative effect of PPARγ is reported in various cancer cell lines including breast, colon, prostate and non-small cell lung cancer." (PMID 25119466, 2014). "Prostacyclin analogs selectively increase peroxisome proliferator-activated receptor gamma (PPARγ) activity in epithelial cells and in non-small cell lung cancer (NSCLC)." (PMID 24216701, 2013). "Preclinical studies from our laboratory demonstrated that activation of PPARγ in human non-small cell lung cancer cell (NSCLC) lines inhibited transformed growth and invasiveness, and promoted a more differentiated phenotype." (PMID 22145026, 2011). "In non-small cell lung cancer, peroxisome proliferator-activated receptor γ (PPARγ), a downstream target of Wnt7A/Fzd9 signaling, inhibits non-small cell lung cancer cell proliferation by up-regulating SPRY4 expression levels through regulating SPRY4 promoter activity." (PMID 38686189, 2024). "Likewise, TZD treatment suppresses proliferation of primary cells derived from human liposarcoma and non-small cell lung cancer (NSCLC) growth in a PPARγ expression dependent manner." (PMID 29137280, 2017). "By contrast, the inhibition of PPARγ expression was found to enhance the response of cervical cancer cells to radiation treatment, while ligand activation of the PPARγ nuclear receptor resulted in the induction of differentiation and apoptosis in non-small cell lung cancer cells." (PMID 31766385, 2019). "Our study examines the potential of selective agonism of PPARG for radiation therapy in non-small cell lung carcinoma (NSCLC)." (PMID 31263479, 2019). "For instance, in non-small cell lung cancer (NSCLC), hypoxia-inducible factor alpha (HIF1α) downregulated PPARG expression, which, subsequently, decreased the expression of uncoupling protein 2 (UCP2)." (PMID 41148824, 2025). "Activation of PPARγ inhibits cell proliferation through up-regulation of expression of the tumor suppressor PTEN in human promyeloid leukemia cells, non-small-cell lung cancer (A549) cells, and PASMCs by inhibition of the PI3K/Akt pathway." (PMID 29527168, 2018).
non-small cell lung carcinoma (continued). "Even with overexpression of dominant-negative PPARγ, pioglitazone and rosiglitazone suppressed PGE2 in human non-small cell lung cancer (NSCLC) A549 cells, suggesting a PPARγ-independent effect of TZDs." (PMID 22934105, 2012). "Nevertheless, the impact of CLA on PPARγ mRNA and protein levels in non-small cell lung cancer (NSCLC) cell lines has not been investigated thus far." (PMID 31993929, 2020). "In non-small-cell lung carcinoma, the antitumorigenic effect of Wnt7a interacting with the specific receptor Fzd9 was mainly mediated through ERK-dependent activation of the nuclear receptor gene PPARγ." (PMID 23304155, 2012).
polycystic ovary syndrome (34 papers, 2007 to 2025). A disorder that manifests as multiple cysts on the ovaries. "Polycystic ovary syndrome has been associated with polymorphisms caused by peroxisome proliferator-activated receptor γ (PPARγ) (Y and Valsala Gopalakrishnan, 2020)." (PMID 38887521, 2024). "The PPARγ agonist valproic acid (an antiepileptic drug) can cause symptoms associated with polycystic ovary syndrome." (PMID 38887521, 2024). "For example, the SNP of PPARγ at P12A (Pro12Ala, rs1801282) was linked to a gynecological disease: polycystic ovary syndrome (PCOS) as PCOS patients with CG genotype showed lower free testosterone and other hormones than that of GG genotype." (PMID 28819354, 2017). "PPARγ Pro12Ala polymorphism is associated with insulin sensitivity and BMI in patients with polycystic ovary syndrome (PCOS)." (PMID 27483259, 2016). "Studies also proposed a relationship between the leptin receptor and PPARγ in the pathogenesis of polycystic ovary." (PMID 41275450, 2025). "Peroxisome proliferator-activated receptor gamma (PPARγ) activation decreased serum testosterone (T) in women with hyperthecosis and/or polycystic ovary syndrome and reduced the conversion of androgens to estradiol (E2) in female rats." (PMID 19536350, 2009). "Furthermore, experiments showed that in mice, PPARγ agonists exhibit a positive effect on ROS levels in polycystic ovary by enhancing the expression of catalase." (PMID 41275450, 2025). "Additionally, the close relationship between PPARγ and polycystic ovary syndrome described in previous studies confirms the role of PPARγ in folliculogenesis." (PMID 32354153, 2020). "On the other hand, treatments that reduce lipotoxicity, such as PPARγ agonists, improve systemic and cellular metabolism of NEFA and have been shown to treat PCOS hyperandrogenemia." (PMID 29971102, 2018). "Rosiglitazone is a PPARγ synthetic activator from the group of thiazolidinediones (TZDs) often used in the treatment of chronic diseases such as type 2 diabetes and other forms of insulin resistance, as seen in polycystic ovary syndrome (PCOS)." (PMID 20144211, 2010). "At the ovarian level, excess androgens suppress granulosa cell proliferation through mechanisms such as upregulating phosphatase and tensin homolog (PTEN) expression, which is PPARγ-dependent, or by disrupting WNT signaling, both of which lead to follicular arrest and polycystic ovary formation." (PMID 41321496, 2025). "Furthermore, Sharma and Singh reported that PPARγ is involved in FSH and PI3K signaling pathways for developing polycystic ovarian syndrome in response to rosiglitazone, an insulin sensitizer." (PMID 27983712, 2016).
Hyperinsulinemia (33 papers, 2008 to 2025). An increased concentration of insulin in the blood. "Mc4r-deficient mice have hyperinsulinemia and hyperinsulinemia stimulates expression of lipogenic genes such as SREBP-1c and PPARγ in liver." (PMID 28030540, 2016). "Our data suggest a direct and sufficient role for hyperinsulinemia in Pparγ-mediated enhancement of hepatic Cd36 expression and thus the subsequent development of hepatosteatosis." (PMID 26085100, 2015). "A recent study showed that fructose-enriched diet (for 8 weeks) activates proinflammatory cytokine IL-6, accompanied by a reduction of PPARγ, without causing hyperinsulinemia, in adipose tissue of rats." (PMID 27066503, 2016). "Under conditions of high circulating FFA and hyperinsulinemia, RGS5 deletion in obese mice significantly promoted the activation of PPARγ and SREBP-1c and led to exacerbated phenotypes, including increased liver weight and enhanced lipid droplet accumulation." (PMID 22272317, 2012). "In agreement with hyperinsulinemia in HFD mice, elevated expressions of IR, insulin receptor substrate 2 (IRS-2), phosphoinositide 3-kinase (PI3K), phosphoinositide-dependent kinase-1 (PDK1), and PPARγ were identified across 24 weeks of feeding." (PMID 33817571, 2021). "However, increased visceral adipose mass and hyperinsulinemia are not expected effects of PPARγ and RXRα activation." (PMID 28824431, 2017).
rheumatoid arthritis (33 papers, 2006 to 2026). A chronic, systemic autoimmune disorder characterized by inflammation in the synovial membranes and articular surfaces. "As PPARγ activation beneficially affects chronic inflammatory diseases such as rheumatoid arthritis, and as gout is closely associated with metabolic diseases, lesinurad’s PPARγ modulation appears as supportive side-activity to its URAT1 inhibitory potency." (PMID 30202096, 2018). "The major finding of our study was that Shentong Zhuyu Decoction can inhibit the inflammatory response, migration, and invasion and promote apoptosis of rheumatoid arthritis fibroblast-like synoviocytes via the MAPK p38/PPARγ/CTGF pathway." (PMID 33511203, 2021). "The peroxisome proliferator-activated receptor gamma (PPARγ) agonists—rosiglitazone and pioglitazone—are being evaluated in ongoing phase II clinical trials for treatment of rheumatoid arthritis and SLE, respectively." (PMID 31640263, 2019). "The PPARγ agonist pioglitazone is studied in clinical trials for rheumatoid arthritis (as well as other chronic inflammatory diseases) where it shows promising activity especially in combination therapy with standard of care." (PMID 30202096, 2018). "Previously, PPARγ was reported to have a negative effect on oxidative stress, and therefore, it was suggested that concomitant use of PPARγ agonists with other treatments will give additional therapeutic benefits against rheumatoid arthritis." (PMID 29065888, 2017). "Furthermore, we observed that NR1C3 (PPARγ) is downregulated in patients with rheumatoid arthritis." (PMID 29065888, 2017). "As such, PPARγ may be an important therapeutic target for rheumatoid arthritis." (PMID 16356194, 2006).